IL10 (interleukin 10)
Diseases named in the same sentence as IL10 in open-access papers (continued):
Sharing a sentence is not in itself a finding about the gene and the disease.
infection (continued). "Other studies have described that co-infection of S. Typhimurium with Plasmodium falciparum enhances the capacity of the bacteria to produce a systemic infection due to the increased production of IL-10 by the host, induced by this parasite." (PMID 28824622, 2017). "In response to microbes, macrophages produce both pro-inflammatory cytokines and IL-10 in order to coordinate a localized and balanced response aimed at efficiently eliminating infection while minimizing damage to surrounding tissue." (PMID 28056086, 2017). "We found that the levels of IL-1α, INF-γ, TNF-α, MCP-1, IL-1β, IL-10, IL-6, IL-27, and IL-17α in the lungs post infection were significantly different between alcohol- and pair-fed mice." (PMID 28604843, 2017). "While we and others have shown IL-10 expression in splenic Breg cells during natural infection with S. mansoni, the contribution of S. mansoni-derived egg antigens was not yet studied." (PMID 28753651, 2017). "In CD4+ T-cells isolated from blood, a decrease in the frequency of IL-10 positive T-cells was observed at 48 and 72h post-infection." (PMID 28880895, 2017). "Cytokine production in vitro - Treatment with CXCL10 (100 ng/mL) in macrophages infected by L. infantum inhibited IL-4 production (significant at 24 h post-infection; p < 0.01) and IL-10 (p < 0.001) in two time periods." (PMID 28767981, 2017). "TH1-cytokines (TNF-α, IFN-γ, IL-12p70) and TH2-cytokines (IL-4, IL-10, IL-13) were measured 8 weeks after initial infection." (PMID 28542175, 2017). "The effect of the feed supplement on the production of pro-inflammatory cytokines IL-8 and INF-γ, the anti-inflammatory cytokine IL-10, the expression of CpSUB1 protease gene during infection was also assessed by quantitative PCR (q-PCR)." (PMID 28883891, 2017). "IL10 is a potent immunomodulatory cytokine that impairs T cell, macrophage and dendritic cell functions in a variety of infection settings." (PMID 28767707, 2017). "To further explore the inflammation response and liver damage of ADE infection, we also detected ALT and IL-10 in the plasma of mice at days 3 post infection by ELISA assay." (PMID 28536674, 2017). "IL-10 is an anti-inflammatory cytokine that participates of Th1, NK cells, and macrophages inhibition during infection." (PMID 28261205, 2017). "Within the lungs of infected mice, LANCL2−/− possessed lower levels of IL-10 and higher levels of IL-6 at day 12 post-infection." (PMID 28270815, 2017). "In experimentally infected dogs of Beagle breed, it was observed high levels of proinflammatory cytokines such as INF-γ, TNF-α, and low IL-10 levels in the acute phase of infection." (PMID 28620374, 2017). "Monofunctional IL10 CD4 T cells were associated with high antigen burden and/or repeated infections, and were associated with protection from symptoms once infected." (PMID 29097996, 2017). "CD4+ cells were the biggest population within IL-10+ T cells throughout infection, with Treg cells representing only a minor population of IL-10–expressing CD4+ T cells." (PMID 28584007, 2017). "Concordant with the upregulation of GFP by CD4+YFP+GFP− T cell–derived memory CD4+ T cells during challenge infection, CD4+ T cells were the predominant source of IL-10 in both the spleen and liver on days 2 and 4 of secondary infection." (PMID 27630165, 2016). "In the current study, we show that both IL-4RαKO and RelmαKO mice had decreased IL-10 production in the skin and increased cellularity in the sdLN after 4x infection." (PMID 27505056, 2016). "CD4+ T cells constituted the dominant source of IL-10 (typically >50% of the total IL-10 response) in all examined organs throughout the course of infection, with the notable exceptions of the spleen (day 14 p.i. or later) and the blood (day 4 p.i.)." (PMID 26459508, 2016).
infection (continued). "Our previous A. butzleri infection studies in gnotobiotic IL-10−/− mice further revealed that in the colon IL-18 mRNA levels were elevated during both the early and late phase of infection, whereas colonic IL-22 mRNA was upregulated during the former only." (PMID 27385977, 2016). "Administration of a single dose of 5 μg of recombinant human IL-10 during bacteremia stages completely cleared the bacteria from the circulation and reversed sustained brain damage within four days post-infection." (PMID 26744349, 2016). "Generally, mice consuming the WB diets displayed lower expression of bacterial recognition genes (Tlr4, RegIIIγ), the defense cytokine gene Relmβ, the Th1 regulatory cytokine gene Ifnγ, and the regulatory cytokine gene Il-10 during peak and late infection." (PMID 28031748, 2016). "As seen in serum, IL-10 concentrations in culture supernatants were also significantly reduced following infection with Δp60 Lm." (PMID 27295349, 2016). "Of note, this deregulated IL-10 expression level observed in PKCtheta−/− CAMs is directly responsible for their bacterial killing defects after infection with S. typhimurium." (PMID 27465248, 2016). "In mice, IL-27 appears to be essential to prevent severe immunopathology after infection with both cutaneous and visceral strains, mainly through the effects of IL-10." (PMID 27867384, 2016). "IL-10 is an important anti-inflammatory cytokine that quells innate and adaptive immune responses during both infection and autoimmunity." (PMID 26991092, 2016). "It is difficult to determine the usefulness of other cytokines, where IFN-γ and IL-10 were elevated late in the infection and the TNF-α, IL-1β, and IL-12p70 cytokines were randomly elevated and did not respond to oseltamivir." (PMID 27110056, 2016). "During coronavirus-infection, IL-10+ CD8+ T cells limit CNS demyelination and slightly increase viral burden as a necessary cost." (PMID 26991092, 2016). "During infection, amastigotes are able to infect new macrophages via IgG antibody receptors (FcγRs), resulting in production of IL-10 at the site of infection and allowing further parasite replication." (PMID 26897363, 2016). "Cytokines including IFN-γ and IL-10 have been studied in several organs with different techniques in dogs with poorly defined clinical classification and different states of infection." (PMID 27260142, 2016). "Significant increases in macrophages (CD45+CD11bhi) of two distinct types were observed in IL-10−/− animals compared to infection-matched WT animals." (PMID 27557867, 2016). "Based upon our RT-PCR analysis of IL-6, IL-10 and TNFα in macrophages infected with legS2 mutants, we can conclude that infection with L. pneumophila legS2 dampens the mRNA expression of cytokines in infected cells." (PMID 26741365, 2016). "Our results suggest that IL-10 is clearly induced at early stages of infection with values peaking at 36 hours post infection." (PMID 27723816, 2016). "In peritoneum, where we observed the most robust cNK cell response, IL-10 was decreased after infection with all the strains." (PMID 27721814, 2016). "We identified that IL-27, which was produced by myeloid cells during the initial days of infection, promoted the generation of IL-10+CD4+ T cells in the spleen." (PMID 27926930, 2016). "In contrast, CD4+YFP+GFP− T cell–derived cells expanded rapidly and upregulated IL-10 expression during secondary infection." (PMID 27630165, 2016). "NK cell IL-10 production was previously observed at late stages of chronic infection by Leishmania donovanni, and during infections by Toxoplasma gondii, and murine cytomegalovirus (MCMV)." (PMID 27295349, 2016). "We also highlight the strategies to target IL-10, MAPK and STAT3 in other infections caused by intracellular pathogens." (PMID 27905994, 2016).
infection (continued). "It was already known that neonatal mice display an increased production of IL-10 early in the course of infection with Lm and after CpG stimulation, but the source of IL-10 in these neonatal studies had been shown to be macrophages and CD5+ B cells." (PMID 27074026, 2016). "Despite the limited maintenance of CD4+YFP+GFP+ T cell after malaria infection, we found that the IL-10 response was amplified during secondary malaria infection compared with primary infection." (PMID 27630165, 2016). "In these studies, we have adapted our mouse model of S. aureus CNS catheter infection to generate infection with S. epidermidis and have used this model to define the contribution of IL-10 to the inflammatory response to CNS catheter infection." (PMID 27737696, 2016). "At day 30 after LCMV-Cl13 infection, the amount of IL-10 expressing iregDC decreased, but those that remained were still identified based on CD39 and CD95 expression." (PMID 26808628, 2016). "The level of immunoregulatory cytokine IL-10 was decreased in PEC after infections with all three strains." (PMID 27721814, 2016). "Taken together, our data showed that IFNγ+IL10+ CD4+ T cells are present during the first-ever symptomatic infection with P. falciparum in naïve individuals as well as in individuals who were last exposed > 5 years ago." (PMID 27802341, 2016). "CD4+ T cells were a major source of IL-10 in all examined organs during malaria infection, with the exception of the spleen after day 14 of infection." (PMID 26459508, 2016). "We specifically investigated the role of early plasma TNF-α and IL-10 as predictors of hypersusceptibility to infections after burn." (PMID 27761434, 2016). "Previously, we reported that CD4+ T cell hypo-responsiveness in the sdLN observed after repeated infection is dependent on IL-10." (PMID 27505056, 2016). "We also used patient samples and an experimental model of VL to investigate how GITR activation influenced cellular immune responses during infection when administered alone or in combination with IL-10 signaling blockade." (PMID 26872334, 2016). "The infection induced the expression of IL-10 but together with the hormone increased its expression (~8-fold)." (PMID 27034592, 2016). "Our results show up-regulated expression of cytokines including TNF-α, IL-6 and IL-10 in 2%DMSO-treated DENV-infected mice and SB203580 treatment significantly reduced the TNF-α, IL-6 and IL-10 expression upon DENV-infection." (PMID 26901653, 2016). "While these studies demonstrate the use of the TNF-α/IL-10 ratio as a biomarker, it has yet to be assessed in the context of trauma and infection prediction." (PMID 27761434, 2016). "Mechanistically, we identified that type I IFNs directly induce T-bet and Blimp-1 expression in CD4 T cells responding to Plasmodium blood-stage infection, which amplifies their production of IL-10 and IFN-γ." (PMID 27732671, 2016). "To address this, we performed a comparative survey on intestinal, extra-intestinal and systemic sequelae upon infection of gnotobiotic IL-10-/- mice with a commensal E. coli strain, the intestinal pathogen C. jejuni and two different A. butzleri strains." (PMID 27438014, 2016). "In cattle, IL-10 production has been detected in the sera of FMDV infected animals with a peak at day 3 or 4 post-infection, which coincides with the development of clinical disease." (PMID 27008425, 2016). "By employing RNA-seq technology and human macrophages we were able to demonstrate that YopM upregulates a number of genes belonging to the immune response, with upregulation of the prominent immunosuppressive cytokine IL-10 already after 1.5 h post infection." (PMID 27300509, 2016). "Contrarily, the expression of anti-inflammatory cytokines (IL-10) showed significant increase in the gut when infection transited from acute to chronic infection." (PMID 27484833, 2016).
infection (continued). "In contrast, among the mouse BMDM types, IL-10 levels were slightly higher in the DBA/2 BMDMs following infection with the attenuated H37Ra strain at an MOI of 0.1." (PMID 27148227, 2016). "We found that IL-6 and IL-10 were both released by hMΦ at 5 hour post-infection by M. tuberculosis and remained significantly detectable in the supernatant 24 hours post-infection (respectively)." (PMID 27384401, 2016). "The early phase of infection is characterized by increased interleukin (IL)-4 and IL-10 production and alterations in the expression of phenotypic markers, which closely resembles the more advanced phases of HIV infection." (PMID 27010200, 2016). "We observed significant attenuation of ΔfmvB in pulmonary mouse infections and reduced levels of GM-CSF, IL-3, and IL-10 in the spleens of ΔfmvB-infected mice on day 5 post-infection, indicating that FmvB is involved in F. tularensis virulence." (PMID 27513341, 2016). "In Mcpt5-Creil10fl/fl mice we observed diminished expression of IL-10 at the 6 h time point following infection which was consistent with findings using Kit mast cell deficiency model." (PMID 26907352, 2016). "NK cells were previously shown to have the capacity to produce IL-10 at late stages of infections by the parasites Leishmania donovani and Toxoplasma gondii and viruses such as murine cytomegalovirus (MCMV)." (PMID 27295349, 2016). "A decrease in spontaneous activity was specific to the IL-10−/− group, and was reduced beginning 8 days post-infection." (PMID 27557867, 2016). "Production of IFN-γ, TNF-α, and IL-6 suggests a type-1 proinflammatory response being developed shortly after infection, while IL-10 production can be related to immune regulation." (PMID 26989699, 2016). "Following infection with C. rodentium, ASF mice treated with CTC and TYL displayed higher expression of Th17- and Th2-associated cytokines (i.e. Il17 and Il10) that are involved in the clearance and resolution of C. rodentium infection." (PMID 27929072, 2016). "Using microscopy to image infection in the skin of living mice, we found that IL-10 is produced by cells that surround areas of virus replication, rather than throughout the tissue as we anticipated." (PMID 26991092, 2016). "We were not able to detect any of the analyzed cytokines in serum samples from control and Lb or La single infected animals, except for IL-10 in La infected group, only at day 25th post infection." (PMID 27446022, 2016). "Although IL-6 and IL-10 were both secreted in the first hours of infection, IL-10 mainly mediates the activation of STAT3 signaling in infected macrophages." (PMID 27384401, 2016). "Numerous viruses have been verified to induce the production of IL-10 with an enhancement of infection by suppression of immune functions." (PMID 26883107, 2016). "FoxO3a−/− macrophages produced significantly lower levels of proinflammatory cytokines, IL-12 and TNF, and higher levels of IL-10 following infection (respectively)." (PMID 27599659, 2016). "During the evolution of the infection, the number of IL-10-producing CD4+ T-cells decreased in both infections." (PMID 27073297, 2016). "To verify that the IL-10 production in the bladder during infection is indeed mast cell dependent, we reconstituted Wsh mice with bone marrow derived mast cells from wild type and from IL-10−/− mice." (PMID 26907352, 2016). "Nevertheless, in both human and murine malaria infections, overproduction or mistimed production of IL-10 can also blunt protective immune responses during infection, resulting in high parasite burdens and morbidity." (PMID 27630165, 2016). "The importance of IL-10-secreting Tr1 cells in limiting immunopathology during highly inflammatory Th1-biased infection is well appreciated." (PMID 27732671, 2016). "Nevertheless, the data indicate the crucial immunoregulatory effect of the IL-10 in recurrent infections." (PMID 27581163, 2016).
infection (continued). "The differential response of IFN-γ, IL-17A and IL-10 has implications for how the two breeds fight infection but also how each breed controls inflammation." (PMID 27069644, 2016). "Infection leads to the upregulation of inflammatory cytokines, such as interleukin-1β (IL-1β), interleukin-10 (IL-10), and tumor necrosis factor-α (TNF-α)." (PMID 28105799, 2016). "In agreement with this, we found that CD4+YFP+GFP− T cell–derived memory cells reactivated quickly during secondary infection, proliferating and upregulating IL-10 GFP expression." (PMID 27630165, 2016). "IL-10−/− mice suffer significant declines in behavioural and physical capacities during infection compared to wildtype." (PMID 27557867, 2016). "We further show that reduced levels of type I interferon and IL-7 and elevated levels of IL-6, IL-8, IL-10 and VEGF strongly associated with severe disease both in primary and secondary infections." (PMID 26982706, 2016). "As infection progressed, the amount of IL-10 expressing cells decreased, but they were still largely observed in the red pulp and marginal zone, although there was also dispersal to other areas by this time." (PMID 26808628, 2016). "In our study, we evaluated cytokines produced in both the acute (IL-1α/β and TNF-α) and the chronic phases (IFN-γ, IL-10, and IL-6) of inflammation/infection and involved in the bone remodeling (IL-6)." (PMID 27478310, 2016). "As expected, at the site of infection, the levels of proinflammatory cytokines IL-12, IFNγ, and IL-17 were increased, and the level of immunoregulatory cytokine IL-10 was decreased, 5 days after infection with three T. gondii strains." (PMID 27721814, 2016). "In agreement, levels of IL-10 are frequently lower in individuals with severe Plasmodium falciparum infections compared with individuals with mild or asymptomatic infections." (PMID 27630165, 2016). "This suggests that IL-10 plays a key regulatory role within these tissue sites in regulating tissue-damaging inflammation during infection." (PMID 26459508, 2016). "CD4+ T cells that produce IFN-γ are the source of host-protective IL-10 during primary infection with a number of different pathogens, including Plasmodium spp." (PMID 27630165, 2016). "Recently, IL-10 produced by Th1 (Tr1) cells was shown to protect host tissues from inflammation induced following infection." (PMID 26765224, 2016). "In particular, intravenous infection with C. albicans is quickly cleared in IL-10−/− mice compared to wild-type mice, which is attributed to more efficient fungal killing by neutrophils." (PMID 27973396, 2016). "The levels of proinflammatory cytokines like TNF-α and interleukin (IL)-1β and Th2 cytokines like IL-10 and IL-4 were measured by reverse transcription qPCR (RT-qPCR) in the liver, lung and spleen of the infected mice at day 7 post-infection." (PMID 26902658, 2016). "The IFN-γ and IL-10 expression level significantly increased at day 6 after infection, later both cytokine levels were decreased to below the detection limit and oseltamivir treatment did not affect the expression levels of these cytokines." (PMID 27110056, 2016). "Noteworthy, it was previously reported in a similar model that IL-10 in the sera of infected mice peaked 2 weeks after infection and then decreased to basal level." (PMID 27901071, 2016). "The best-described immune-response-limiting protein is the cytokine interleukin-10 (IL-10), which is produced during infections with disparate pathogens including viruses, bacteria, and parasites." (PMID 26991092, 2016). "In this study, TNF-α/IL-10 ratio was found to be highly predictive of hypersusceptibility to infections, with high AUROC and high sensitivity and specificity." (PMID 27761434, 2016). "In Mtb, IL-10 also block the migration of T cell to the site of infection most commonly impairing the recruitment of Th1 cells to the lungs of infected mice." (PMID 27905994, 2016).